IL33 (interleukin 33)
Diseases named in the same sentence as IL33 in open-access papers (continued):
Sharing a sentence is not in itself a finding about the gene and the disease.
ulcerative colitis (35 papers, 2013 to 2025). An inflammatory bowel disease involving the mucosal surface of the large intestine and rectum. "Two different polymorphisms were found to contribute to the risk and the IL-33 rs3939286 was increased in frequency in patients with extensive ulcerative colitis." (PMID 37761298, 2023). "The ST2/IL33 signalling pathway has been associated with ulcerative colitis (UC)." (PMID 28860510, 2017). "The ‘IL-33 and its receptor IL1RL1 axis’ has been associated with inflammation and stimulation of the Th2 immune response in ulcerative colitis where levels of IL-33 are significantly increased." (PMID 35576023, 2022). "Existing findings revealed that miR‐378a‐3p elevated IL‐33 expression in an inflammatory environment, thereby inducing the pathogenesis of ulcerative colitis." (PMID 35582765, 2022). "Defining mechanisms that induce epithelial IL-33 are of particular interest in ulcerative colitis (UC), one of the main entities of IBD10." (PMID 35798804, 2022). "IL-33 expression was previously found to be induced in inflamed colonic tissues from ulcerative colitis patients." (PMID 34400793, 2022). "IL-33 expression levels are increased and positively correlated with disease severity in patients with ulcerative colitis and Crohn’s disease, as well as in a mouse model." (PMID 36291105, 2022). "This is also supported by the amelioration of ulcerative colitis animal models where IL-33 signaling was blocked." (PMID 33133101, 2020). "IL-33 is involved in gastrointestinal pathologies, such as ulcerative colitis, where IL-33 is upregulated and believed to potentiate Th2 responses." (PMID 33133101, 2020). "In the present study, we investigated the relative gene expression levels of TSLP and IL-33 molecules in ulcerative colitis." (PMID 30868311, 2019). "Recent findings suggest that enterocyte-derived IL-33 is induced and maintained by inflammatory mediators, because IL-33 is detected in the nuclei of epithelial cells of colonic crypts in acute ulcerative colitis, but undetectable during remission." (PMID 28710436, 2017). "We have characterized the expression of IL-33 in well-defined clinical stages of ulcerative colitis." (PMID 27748438, 2016). "Taken together, this implies that the role of IL-33 in the pathogenesis of ulcerative colitis varies according to phases of inflammation and mucosal healing." (PMID 27748438, 2016). "The ST2/IL-33 pathway has been related to ulcerative colitis (UC), and soluble ST2 (sST2), to disease severity." (PMID 27565556, 2016). "Because in this study it was also found that IL-33 was increased in the colon of patients with active ulcerative colitis, this suggests the IL-33 pathway has potential for the development of novel therapies." (PMID 27578924, 2016). "Other studies investigated the level of cytokine expression in tissue from patients and found increased colonic mucosal IL-33 in patients with active ulcerative colitis, while IL-22 was found to be increased in active Crohn's disease as a response to damage." (PMID 27578924, 2016). "IL-33 is highly expressed by intestinal ECs and inflammatory infiltrates in ulcerative colitis, with IL-33 cleavage products being detected in the serum." (PMID 25101088, 2014). "IL-33 is involved in the pathogenesis of different inflammatory and allergic disorders such as rheumatoid arthritis, asthma, psoriasis and ulcerative colitis." (PMID 24725541, 2014). "We evaluated the association of six SNPs in IL-33 and IL1RL1 genes, in 805 Crohn’s disease (CD), 816 ulcerative colitis (UC), and 752 controls, using Taqman." (PMID 23634226, 2013). "The nuclear alarmin interleukin-33 (IL-33) is upregulated in the colonic mucosa of acute ulcerative colitis (UC) and may represent an early instigator of the inflammatory cascade." (PMID 35798804, 2022). "Intriguingly, miR‐378a‐3p could increase the IL‐33 expression upon inflammation, which can exacerbate the pathogenesis of ulcerative colitis." (PMID 35582765, 2022).
ulcerative colitis (continued). "Thus, inhibition of miR-378a-3p by inflammation enhanced IL-33 protein levels in IEC, highlighting genes and microRNAs associated with metabolic shifts in ulcerative colitis, possibly impacting on soluble inflammatory factors." (PMID 31824476, 2019). "Association of IL-33 and IL1RL1 genes markers with ulcerative colitis (UC); case-control study." (PMID 23634226, 2013). "Interestingly, Casp−/− mice are more susceptible to inflammation-induced tumorigenesis in the colon, while IL-33 was recently found to be increased in ulcerative colitis." (PMID 23382912, 2013). "Moreover, circulating IL-33 levels were shown to be increased in patients with different immune-inflammatory diseases such as rheumatoid disorders, systemic sclerosis, and ulcerative colitis." (PMID 24725541, 2014). "The levels of IL-33, a member of the IL-1 family, and its ligand-related protein, ST2, were increased in the mucosa as well as in the serum of ulcerative colitis patients, and a good correlation was found with disease severity." (PMID 37761298, 2023). "A recent study shows that IL-33 is present in the nuclei of enterocytes in scattered colonic crypts in acute ulcerative colitis, but is not present in these cells at remission." (PMID 28710436, 2017). "IL-33 was present in the nuclei of enterocytes in scattered colonic crypts in acute ulcerative colitis, but was not present in these cells at clinical disease remission." (PMID 27748438, 2016). "A clinical study showed that mRNA expression levels of IL-33 were decreased in biopsy specimens of ulcerative colitis patients compared with the control group, and a negative correlation was observed between IL-33 expression and the severity of ulcerative colitis." (PMID 36291105, 2022).
glioma (34 papers, 2018 to 2025). A benign or malignant brain and spinal cord tumor that arises from glial cells (astrocytes, oligodendrocytes, ependymal cells). "Conversely, loss of nuclear IL-33 crippled TAMs recruitment remarkably, inhibited glioma growth, and prolonged survival." (PMID 35600367, 2022). "On the other hand, a recent study demonstrated that glioma-derived IL-33 correlated with increased tumor-associated macrophages/microglia in human specimens and in mice with intracerebral xenografts." (PMID 34079543, 2021). "Next, to assay the in vivo effects of glioma-derived IL-33, tumor cells expressing IL-33, or the nuclear localization-deficient IL-33 were implanted into the brains of SCID mice and monitored for tumor burden." (PMID 33020472, 2020). "The existence of these peripheral myeloid cells within the IL-33-expressing tumors supports the association of glioma-derived IL-33 with mediators that promote recruitment of cells from the circulation into the brain." (PMID 33020472, 2020). "Conversely, loss of nuclear IL-33 cripples recruitment, dramatically suppresses glioma growth, and increases survival." (PMID 33020472, 2020). "Recently, researchers found that overexpression of IL-33 was associated with poor prognosis of patients with glioma and enhanced the tumorigenic activity of rat glioma cells." (PMID 32003751, 2020). "Our results also indicate that knockdown of IL-33 or ST2 expression in glioma cells causes a decrease in TNC expression at both the transcriptional and translational levels." (PMID 31889095, 2019). "Elevated levels of interleukin-33 have been associated with poor prognosis in patients with glioma." (PMID 33020472, 2020). "Clinically, IL-33 expression was associated with poor survival in patients with glioma." (PMID 32003751, 2020). "Furthermore, our immunohistochemical data demonstrates that IL-33+ syngeneic glioma, and IL-33+ xenografts associate with an increase in Iba1+ cells in the tumor-bearing hemisphere." (PMID 33020472, 2020). "Moreover, nuclear IL-33 proteins in cooperation with chromatin-associated proteins regulate glioma nuclear structure, which might be crucial for glioma progression and malignancy." (PMID 34744630, 2021). "Analogously, De Boeck and coworkers demonstrated that suppression of the glioma-released, TME-altering factor IL-33 stunts recruitment of peripheral innate immune cells and glioma progression." (PMID 41227348, 2025). "Here, we demonstrate that IL-33 expression is primarily restricted to the oligodendrocyte lineage in mouse models of glioma." (PMID 39931535, 2025). "To assess the role of the IL-33/ST2 axis in glioma growth in vivo, we injected CT-2A glioma cells into the brains of ST2-deficient mice and monitored their tumor burden and survival outcome, compared to that of wild-type (wt) mice." (PMID 39931535, 2025). "Secretion of IL-33 from glioma cells recruits TAM and microglia and promotes a pro-tumorigenic environment." (PMID 37509400, 2023). "In this study, we also showed that LAIR1 remarkably promoted the production of CCL5, TGFβ2, and IL33 in glioma cells, in a nuclear FAK-dependent manner." (PMID 37845206, 2023). "For example, a large proportion of gliomas secrete IL-33 (interleukin-33), which promotes recruitment of innate immune cells to create a tumor-promoting microenvironment." (PMID 35690784, 2022). "De Boeck and colleagues recently suggested that both the nuclear and secreted form of IL-33 are present within tumour cells in ~50% of human glioma specimens and GBM murine models." (PMID 36555253, 2022). "PRDM1 has been reported to affect the progression of glioma, and IL-33 has been demonstrated to promote the stemness of tumor stem cells." (PMID 35927251, 2022). "Using multiplex cytokine/chemokine analysis, these authors further demonstrated that nuclear IL-33 facilitates tumour growth by triggering glioma-mediated expression of inflammatory cytokines (LIF, IL-6, IL-8, IL-1RN, IL-1β and secreted IL-33." (PMID 36555253, 2022).
glioma (continued). "This phenomenon seems to indicate that IL-33 negatively regulates microglial migration in gliomas, explaining the involvement of IL-33 in active glioma growth and invasion." (PMID 36439205, 2022). "Inexplicably, genetic knockdown of IL-33 results in elevated CCL7 in glioma cells and further promotes microglial migration." (PMID 36439205, 2022). "Despite different forms of IL-33 administration in diseases such as intracerebral hemorrhage, spinal cord injury, glioma, and AD, an increase in the percentage of microglia expressing M2 markers (Arginase-1 or CD206) is consistently induced by IL-33 treatment." (PMID 36439205, 2022). "On the other hand, another xenograft glioma study found that glioma-secreted IL-33 with its nuclear domain deleted was sufficient for microglial recruitment." (PMID 36439205, 2022). "The group reported that ST2 expression was minimal on glioma cells and that nuclear IL-33 mediated the release of inflammatory cytokines from glioma cells and was required for the recruitment of M2 protumorigenic macrophages." (PMID 34079543, 2021). "Despite that, IL-33 is known to foster the formation of the inflammatory tumor microenvironment and facilitate glioma progression, evidence showing nuclear IL-33 function is still poor." (PMID 34744630, 2021). "Altogether, the upregulation of nuclear IL-33 expression was along with an increase in the expression of DNA repair genes, contributing to the desensitization of glioma cells to DNA damaging agents." (PMID 34744630, 2021). "Treated with JNK inhibitor blocked the effect of IL-33 on promoting cell migration and invasion in both glioma cell lines." (PMID 32003751, 2020). "We found a substantial increase in p-STAT3 in both the glioma cells expressing IL-33 and the Iba1+ cells, a result consistent with a bidirectional signaling between the glioma cells and the Iba1+ TAM." (PMID 33020472, 2020). "In our recent study we focussed on IL-33 based on its increasing relevance in tumorigenesis including glioma." (PMID 33447733, 2020). "We proposed that glioma-derived IL-33 orchestrates the brain tumor microenvironment by activating resident microglia and/or recruiting monocyte/macrophage innate immune cell populations from the cir-culation to promote gliomagenesis." (PMID 33447733, 2020). "Next, to functionally assess these IL-33-regulated factors, BMDM were exposed to glioma-derived CM from IL-33+, IL-33-ΔNLS, and IL-33− glioma cells." (PMID 33020472, 2020). "In this research we examined the expression of IL-33 was significantly increased in glioma tissues and cell lines." (PMID 32003751, 2020). "Here the authors show that glioma-derived IL-33 modulates a pro-tumorigenic immune microenvironment by activating resident and recruiting peripheral innate immune cells." (PMID 33020472, 2020). "Third, we determined that nuclear IL-33 mediates the secretion of a number of inflammatory cytokines from glioma cells." (PMID 33020472, 2020). "Of interest, we found that these glioma-associated microglia were nearly threefold higher in the IL-33-expressing xenografts than the control, an observation supporting IL-33 as a driver of an activated glioma microenvironment." (PMID 33020472, 2020). "To extend these results, we used an independent cohort of GBM specimens (tissue microarray (TMA) containing 70 patient specimens) and found that 12/64 (18.8%) had high IL-33 expression that was predominately localized within the nucleus of glioma cells." (PMID 33020472, 2020). "Secretion of IL-33 from glioma cells is minimal in vitro and was only observed when the tumor cells were implanted in vivo." (PMID 33447733, 2020). "Knockdown IL-33 or blocked the ST2 with anti-ST2 antibody in combination with TMZ decreased the proliferation of glioma cells more significantly." (PMID 32003751, 2020). "The molecular mechanisms of how IL-33 regulates glioma invasion, stemness and mesenchymal transition need to be further investigated." (PMID 32003751, 2020).
glioma (continued). "We find that IL-33 expression in a large subset of human glioma specimens and murine models correlates with increased tumor-associated macrophages/monocytes/microglia." (PMID 33020472, 2020). "As in the case of the human glioma cells, the murine glioma cells also express IL-33 in two locales, the nucleus and secreted." (PMID 33020472, 2020). "In the context of wildtype IL-33 which is both in the nucleus of the glioma cell and secreted, we propose that nuclear IL-33 regulates or facilitates the expression of a large number of genes which includes several cytokines and chemokines." (PMID 33447733, 2020). "Although very little IL-33 is released from glioma cells in vitro, substantial quantities of IL-33 detected in the interstitial secretome in vivo." (PMID 33020472, 2020). "Kaplan-Meier survival analyses showed that glioma patients with high expression levels of IL33 had shorter overall survival than those with low levels, the result of ST2 expression was the same." (PMID 32003751, 2020). "We confirmed the expression and secretion of a large number of inflammatory cytokines in IL-33+ glioma cells and, with the exception of CCL2, indicate regulation of these genes by nuclear IL-33." (PMID 33020472, 2020). "Here, we demonstrated that IL-33 was a critical tumor promoter during epithelial to mesenchymal transition and stemness in glioma." (PMID 32003751, 2020). "In this study, we showed that glioma cells and tissues expressed higher levels of IL-33 and its receptor ST2 compared to normal brain." (PMID 32003751, 2020). "Secretion of IL-33 from glioma cells acts to recruit monocytic cells from the circulation that contribute to the cellular composition within the brain tumor environment." (PMID 33020472, 2020). "We also observed that glioma-derived IL-33 results in an increase in p-STAT3 in both glioma cells and Iba1+ stromal cells, with subsequent loss of p-STAT3 within glioma cells deficient for nuclear IL-33 (ΔNLS)." (PMID 33020472, 2020). "Here, we found that the BMDM present in the IL-33+ glioma together with resident microglia, have a number of distinct transcriptional networks expressing both pro-inflammatory (M1) and alternatively activated (M2) genes simultaneously." (PMID 33020472, 2020). "Administration of recombinant human IL-33 promotes glioma cell motility, invasion, EMT and stemness." (PMID 32003751, 2020). "In both the human and mouse IL-33+ glioma models there was a correlation with high macrophage/microglial infiltration with tumor-promoting capacity." (PMID 33020472, 2020). "Ectopic expression of the full-length IL-33 in both glioma lines resulted in a dramatic increase in tumor growth with a concomitant increase in Iba1+ TAMs and a significant decrease in the overall survival (p < 0.0001)." (PMID 33020472, 2020). "We had confirmed the expression of ST2 was increased in human gliomas compared with normal tissues and IL-33 treatment increased ST2 expression in glioma cells." (PMID 32003751, 2020). "Together these data suggest that IL-33 expressing glioma cells establish a pro-tumorigenic yet anti-inflammatory environment that mediates a dramatic increase in tumorigenesis." (PMID 33020472, 2020). "Strikingly, glioma derived expression of IL-33 correlates with a dramatic decrease in overall survival of tumor-bearing animals and thus supports its role as an influential factor in gliomagenesis." (PMID 33447733, 2020). "Of specific interest was the observation that the IL-33-driven environment activated Stat3 signaling, as indicated by an increase in phosphorylated (p)-STAT3 (pY705), a state that has been associated with glioma progression." (PMID 33020472, 2020). "Independent it is clear by the data provided herein that the IL-33 environment educates TAMs to drive glioma progression and that the nuclear function of IL-33 is required." (PMID 33020472, 2020).